RNASEL (ribonuclease L)
Description:
Endoribonuclease that functions in the interferon (IFN) antiviral response. In INF treated and virus infected cells, RNASEL probably mediates its antiviral effects through a combination of direct cleavage of single-stranded viral RNAs, inhibition of protein synthesis through the degradation of rRNA, induction of apoptosis, and induction of other antiviral genes. RNASEL mediated apoptosis is the result of a JNK-dependent stress-response pathway leading to cytochrome c release from mitochondria and caspase-dependent apoptosis. Therefore, activation of RNASEL could lead to elimination of virus infected cells under some circumstances. In the crosstalk between autophagy and apoptosis proposed to induce autophagy as an early stress response to small double-stranded RNA and at later stages of prolonged stress to activate caspase-dependent proteolytic cleavage of BECN1 to terminate autophagy and promote apoptosis. Might play a central role in the regulation of mRNA turnover. Cleaves 3' of UpNp dimers, with preference for UU and UA sequences, to sets of discrete products ranging from between 4 and 22 nucleotides in length. Involved in intercellular immune signaling. Cross-activated by 2',5'-oligoadenylates (2-5A) previously generated in RNA virus-infected cells, triggers type I interferon signaling in uninfected neighboring cells to limit local spread of infection.
Synonyms: RNS4; PRCA1
Tractability: Small molecule: a structure with a bound ligand is known. PROTAC: ubiquitination databases record sites on it; its protein half-life has been measured; a small molecule that binds it is known.
Target class: Enzyme; Hydrolase
Gene: Protein-coding gene on chromosome 1 (182,573,634 to 182,589,272, reverse strand). Ensembl gene ENSG00000135828.
Subcellular location: Cytoplasm; Mitochondrion
Subcellular location (Human Protein Atlas): Cytosol
Pathways (Reactome):
Immune System: Interferon alpha/beta signaling; OAS antiviral response
Gene Ontology:
Molecular function: protein binding; RNA binding; RNA nuclease activity; RNA endonuclease activity; ATP binding; protein kinase activity; ribonucleoprotein complex binding; rRNA binding
Biological process: defense response to virus; negative regulation of viral genome replication; positive regulation of transcription by RNA polymerase II; protein phosphorylation; RNA processing; mRNA processing; regulation of gene expression; regulation of RNA metabolic process; rRNA processing
Cellular component: cytosol; mitochondrial matrix; cytoplasm; mitochondrion; nuclear matrix
Genetic constraint (gnomAD): Loss-of-function variants: 30 observed, 49 expected, observed/expected ratio (o/e) 0.61, 90% interval 0.46 to 0.83. The upper end of that interval is the gene's LOEUF score, 0.83, which puts it in group 3 of 6, group 1 being the genes least tolerant of losing a copy. Missense variants: 823 observed, 915.98 expected, observed/expected ratio (o/e) 0.9, 90% interval 0.85 to 0.95. Synonymous variants: 327 observed, 350.72 expected, observed/expected ratio (o/e) 0.93, 90% interval 0.85 to 1.02.
Homologues: Orthologues: chimpanzee RNASEL (97% identical), macaque RNASEL (92% identical), pig RNASEL (71% identical), dog RNASEL (70% identical), mouse Rnasel (64% identical), rat Rnasel (63% identical), rabbit RNASEL (56% identical).
Diseases named in the same sentence as RNASEL in open-access papers:
RNASEL is named in the same sentence as 88 diseases in open-access papers, as found by Europe PMC text mining. Sharing a sentence is not in itself a finding about the gene and the disease. The quoted sentences say what the papers report.
viral infection (155 papers, 2005 to 2026). "RNASEL triggered autophagy in response to viral infections and was associated with DNA damage and apoptosis of cancer cells." (PMID 34746127, 2021). "In order to consider the association between RNASEL mutation and viral infection, we amplified part of the RNASEL gene by PCR and determined the status of the R462Q RNASEL polymorphism." (PMID 21447170, 2011). "This current study analyzed associations between viral infections, the R462Q variant of RNASEL, and PC." (PMID 20576103, 2010). "In the present study the association between viral infection, prostate cancer and the RNASEL variant are assessed." (PMID 20576103, 2010). "The best characterized HPC1 gene encodes RNaseL, a protein involved in response to dsRNA produced during viral infections or certain other aberrant RNAs." (PMID 17280610, 2007). "The 2'-5'-oligoadenylate synthetase (OAS)/ribonuclease L (RNase L) system is an innate immunity pathway that responds to pathogens and is associated with the induction of viral and cellular RNAs degradation, thereby blocking viral infections." (PMID 37703107, 2023). "Indeed, viral infection with xenotropic murine leukemia virus-related virus (XMRV) has been observed to be more common in prostate cancers of individuals homozygous for the RNASEL rs486907 variant." (PMID 24699816, 2014). "Mutations in either the OAS1 or RNASEL genes may also modulate the outcome of WNV-induced disease or other viral infections in horses." (PMID 17822564, 2007). "Ribonuclease L (RNase L) as an innate immune response pathway is triggered by exogenous and endogenous abnormal dsRNA under viral infection and dyshomeostasis, thereby activating the immune responses." (PMID 38473966, 2024). "For example, the latent endoribonuclease, ribonuclease L (RNase L), can be activated in response to viral infection when dsRNA is recognized by 2ʹ-5ʹ-oligoadenylate sythetases (OASs), which produce 2ʹ-5ʹoligo(A)." (PMID 38321453, 2024). "One mechanism by which this occurs is through the activation of ribonuclease L (RNase L), an enzyme that degrades mRNA in response to exogenous nucleic acid insults, such as those arising from viral infection." (PMID 37631003, 2023). "During early viral infections, ribonuclease L (RNase L), another ISG product, activates autophagy to inhibit viral multiplication." (PMID 36875122, 2023). "Ribonuclease L (RNase L) initiates rapid and widespread degradation of cellular mRNAs in response to double-stranded RNA or viral infection." (PMID 36318584, 2022). "In higher vertebrates, this process is regulated by interferon (IFN), produced during a viral infection through the activation of the ubiquitous cellular latent endoribonuclease, ribonuclease L (RNase L)." (PMID 33670646, 2021). "RNASEL (Ribonuclease L) limits viral infections by degrading viral and cellular RNA, inducing autophagy and apoptosis, and producing RNA degradation products that enhance type I interferon (IFN) production via RIG-I receptors." (PMID 34671358, 2021). "For instance, OAS1 and OAS2 are responsible for the activation of ribonuclease L, which is part of the innate immune defense, during viral infection." (PMID 32155831, 2020). "Another ISG product, ribonuclease L (RNase L), can degrade and produce small viral RNA fragments, which activates autophagy to suppress viral multiplication during early viral infections." (PMID 30717138, 2019). "In fact, only OAS3 in the human OAS family can initiate the OAS/RNaseL pathway upon viral infection." (PMID 30587119, 2018). "In mammals, ribonuclease L (RNase-L) was originally recognized as a key factor in response to viral infection in innate immunity." (PMID 28399925, 2017). "Knockdown of RNASEL, a gene involved in innate immunity to viral infection, rescued RD cells from DUX4 lethality (DUX4 Z-Score = 3.71) and had minimal effect on the doxycyline induction of the luciferase transgene (Luciferase Z-Score = -0.07)." (PMID 28273136, 2017).
viral infection (continued). "ISGs encode a wide variety of proteins, such as RNA-activated protein kinase (PKR), oligoadenylate synthase (OAS) and ribonuclease L (RNase L), that play crucial roles in immune responses against viral infections." (PMID 25165812, 2014). "Ribonuclease L (RNase L) is an antiviral endoribonuclease of the innate immune system, which is induced and activated by viral infections, interferons, and double stranded RNA (dsRNA) in mammalian cells." (PMID 25254215, 2014). "RNASEL is a ribonuclease that degrades viral and cellular RNA and can produce apoptosis in viral infection." (PMID 24282788, 2013). "One theory that explains how viral infections may lead to T1D involves the interferon (IFN)-α-activated latent ribonuclease (RNAseL) signaling pathway." (PMID 36307540, 2022). "The potential role of OAS3 in the recognition of CpG- and UpA-high mutants is consistent with its demonstrated preferential role in mediating RNAseL responses to a wide range of virus infections, and the frequent inactivity of OAS1 (and OAS2) in antiviral defence." (PMID 31276592, 2019). "Human OAS1 and OAS2 have proved to be ineffective for activation of RNaseL upon virus infection." (PMID 30587119, 2018). "The inclusion of genetic and epigenetic variation into association and functional studies may provide novel findings about RNASEL activity during viral infections." (PMID 26553552, 2016). "In control of viral and cellular growth, the role of the 2-5A system suggests that defects in the 2-5A-dependent RNASEL gene could result in decreased immunity to virus infections and cancer." (PMID 26236721, 2015). "Discrepancies between large studies of hereditary prostate cancer suggest that environmental factors, such as viral infection, may modulate the impact of RNASEL variation on carcinogenesis." (PMID 24699816, 2014). "In addition, ribonuclease L (RNase L) can also mediate circRNA degradation after viral infection." (PMID 33710802, 2021). "It should be noted that overexpression of hsa-miR-29a-3p in ME/CFS patients may contribute to the reduction of their ability to respond to certain viral infections by targeting RNase L (ribonuclease L), which is known among others, for its central role in innate immunity." (PMID 33184353, 2020). "As the result of viral infection, there is an increase in OAS expression and activation which leads to synthesis of 2-5A from ATP and activation of RNaseL." (PMID 37209263, 2023). "In response to a viral infection, the interferon-induced ribonuclease L (2′,5′-oligoadenylate (2–5A) synthetase (OAS) -RNase L, RNAse L) is activated, which cleaves cellular and viral RNA." (PMID 34680956, 2021). "The well-established role for ribonuclease L is to cleave viral and cellular RNA as the final executor in the OAS/ribonuclease L innate immune pathway in response to viral infection." (PMID 33203179, 2020). "The induction of RNASEL in response to IFN in bats may give an extra layer of antiviral protection as knock-out experiments showed that black flying fox cells lacking RNASEL had an increased susceptibility to viral infection." (PMID 33363045, 2020). "In the viral infection process, SGs can recruit a variety of proteins related to innate immunity, such as PKR, 2′-5′ oligoadenylate synthetase (OAS) and ribonuclease L (RNase L), to protect cells." (PMID 32703221, 2020). "The HCV UpA dinucleotide frequency was significantly associated with the IFNL4 SNP rs12979860 genotypes; interestingly, ribonuclease L (RNase-L), an ISG that cleaves viral RNA to control viral infections in animals, targets both UpA and UpU dinucleotides." (PMID 31478835, 2019). "It was previously proposed that a host nuclease, RNaseL, can generate self-RNA ligands for the RIG-I and MDA5 pathways in response to viral infection." (PMID 19936053, 2009).
viral infection (continued). "Ribonuclease L does cleave rRNA, but this is a step of apoptosis as a result of extreme cellular stress such as viral infection, and it is not a normal processing of rRNA for the maturation of rRNAs." (PMID 33203179, 2020). "In particular, they upregulated transcription of the genes involved in cellular response to viral infection and foreign genetic material, such as RIG-I (DDX58), OAS1, MYD88, RNASEL, PKR (EIF2AK2), as well as interferon-dependent transcription factor STAT and IRF families." (PMID 29986702, 2018). "After viral infection, the immune system starts the production of interferons, which induce the expression of the 2'-5'-oligoadenylate synthetase (OAS) family of interferon stimulated genes and activate the endoribonuclease RNaseL that provides antiviral protection by viral RNA degradation." (PMID 36778388, 2023). "While OAS3 is the primary activator of RNASEL during most viral infections, oncogenic cells failed to express ectopic OAS3 at levels that could be validated by immunoblot." (PMID 35594991, 2022). "While the RNASEL gene was shown to play a role during Dengue virus infection, MEFV and MASP2 deficiencies may manifest subclinically, and CFTR deficiency leads to severe outcomes that predominantly involve opportunistic bacterial rather than viral infections." (PMID 39062917, 2024). "In cases where there is no viral infection, circRNA-RNA duplexes bind and hamper double-stranded RNA-activated protein kinase (PKR) due to ribonuclease L (RNase L) inactivity." (PMID 37993909, 2023).
prostate carcinoma (90 papers, 2003 to 2025). A carcinoma that arises from epithelial cells of the prostate gland. "One of these genes is RNASEL, which plays a role in antiviral defense and apoptosis, and has been linked to hereditary prostate cancer in some studies, although this association is controversial, with multiple studies failing to replicate these findings." (PMID 40433050, 2025). "RNASEL mutations can reduce the enzymatic activity and impair the proapoptotic function of its protein, contributing to the development of human prostate cancer." (PMID 40839607, 2025). "A separate group of Oas-RNaseL pathway alleles is thought to cause pathway suppression and to be involved in the genesis of prostate cancer." (PMID 35505346, 2022). "The study described here was undertaken to determine the involvement of R462Q and D541E variants of the RNASEL gene in prostate cancer in the Burkinabe population." (PMID 35655265, 2022). "In fact, some mutations in the tumor-suppressor gene RNASEL have been found to lead to ribonuclease L dysfunction, inflammation, infection, and increased risk of prostate cancer, suggesting links between innate immunity and tumor suppression." (PMID 36424644, 2022). "Previous studies on the RNASEL variant D541E indicated that the GG and TT genotypes were associated with an increased risk of prostate cancer in some Japanese and European-American populations, respectively." (PMID 35655265, 2022). "Missense point mutations of RNASEL gene resulting in aberrant RNASEL structure (arginine to glutamine substitution at position 462) followed by defective function were documented in some families with hereditary prostate cancer." (PMID 35565367, 2022). "Other cancer studies found that allelic variation in RNaseL was observed to be associated with increased risk of prostate cancer and the increased risk of higher tumor grade, together with an increased level of inflammation markers." (PMID 35505346, 2022). "The aim of this study was to analyze the carriage of RNASEL R462Q and D541E mutations and risks factors in patients with prostate cancer in the Burkina Faso." (PMID 35655265, 2022). "Results demonstrated a correlation between increased cancer risk and RNaseL SNP rs3738579 in these cancer types, suggesting that RNaseL is not limited to prostate cancer but rather is a general cancer susceptibility gene." (PMID 34809722, 2021). "Research has unraveled a correlation between RNaseL mutations and prostate cancer, leading to the classification of RNaseL gene as a prostate cancer susceptibility gene." (PMID 34809722, 2021). "In accordance, we found a RNASEL stopgain variant in a patient with a diagnosis of prostate cancer and a father dead at 62 years of prostate cancer." (PMID 34026625, 2021). "The most studied gene linked to prostate cancer susceptibility is ribonuclease L (RANSEL), which encodes an enzyme that is induced by interferon that degrades viral RNA and modify innate immune responses." (PMID 33076397, 2020). "The general goal of this pooled analysis is to quantitatively analyze previous studies to understand the true relationship between RNASEL polymorphism and prostate cancer." (PMID 29088852, 2017). "In general, 11,522 prostate cancer patients and 10,976 control subjects with the RNASEL Arg462Gln polymorphism were evaluated." (PMID 29088852, 2017). "To assess the impact of RNASEL Arg462Gln polymorphism on prostate cancer risk, we conducted a meta-analysis of all available studies including 11,522 patients and 10,976 control subjects." (PMID 29088852, 2017). "Various studies have used polymorphisms in the RNASEL gene to evaluate prostate cancer risk but studies that show an association between RNASEL Arg462Gln (1385G>A, R462Q, rs486907) polymorphism and prostate cancer risk are somewhat inconclusive." (PMID 29088852, 2017). "Extensive epidemiological studies had been conducted to explore the association between RNASEL polymorphism and prostate cancer risk." (PMID 29088852, 2017).